POLR2MP1 (POLR2M pseudogene 1)
Synonyms: GLURR2; formerly GRINL1B; GCOM2
Gene: Processed pseudogene on chromosome 4 (68,038,544 to 68,039,647, forward strand). Ensembl gene ENSG00000227725.
Diseases named in the same sentence as POLR2MP1 in open-access papers:
POLR2MP1 is named in the same sentence as 1 disease in open-access papers, as found by Europe PMC text mining. Sharing a sentence is not in itself a finding about the gene and the disease.
POLR2MP1 shares sentences with these, for which no sentence is quoted: tumour (1 paper).